HPD (4-hydroxyphenylpyruvate dioxygenase)
Description:
Catalyzes the conversion of 4-hydroxyphenylpyruvic acid to homogentisic acid, one of the steps in tyrosine catabolism. In addition may act as a N6-methyltransferase that methylates adenosine residues at the N(6) position of some RNAs.
Synonyms: 4HPPD; HPPDase; PPD; 4-HPPD; GLOD3; HPPD
Tractability: Small molecule: an approved drug acts on it; a structure with a bound ligand is known; a high-quality ligand is known; it belongs to a druggable protein family. Antibody: UniProt places it where antibodies can reach, with medium confidence. PROTAC: ubiquitination databases record sites on it; its protein half-life has been measured; a small molecule that binds it is known.
Target class: Enzyme; Oxidoreductase
Gene: Protein-coding gene on chromosome 12 (121,839,277 to 121,863,596, reverse strand). Ensembl gene ENSG00000158104.
Subcellular location: Cytoplasm; Endoplasmic reticulum membrane; Golgi apparatus membrane; Nucleus
Subcellular location (Human Protein Atlas): Nuclear speckles
Pathways (Reactome):
Metabolism: Tyrosine catabolism
Gene Ontology:
Molecular function: 4-hydroxyphenylpyruvate dioxygenase activity; mRNA m(6)A methyltransferase activity; protein binding; protein homodimerization activity; oxidoreductase activity, acting on single donors with incorporation of molecular oxygen
Biological process: L-tyrosine catabolic process; aromatic amino acid metabolic process; L-phenylalanine catabolic process
Cellular component: cytoplasm; extracellular exosome; nucleus; cytosol; endoplasmic reticulum membrane; Golgi membrane
Genetic constraint (gnomAD): Loss-of-function variants: 35 observed, 54.93 expected, observed/expected ratio (o/e) 0.64, 90% interval 0.49 to 0.85. The upper end of that interval is the gene's LOEUF score, 0.85, which puts it in group 3 of 6, group 1 being the genes least tolerant of losing a copy. Missense variants: 422 observed, 516.69 expected, observed/expected ratio (o/e) 0.82, 90% interval 0.75 to 0.88. Synonymous variants: 180 observed, 205.34 expected, observed/expected ratio (o/e) 0.88, 90% interval 0.78 to 0.99.
Gene-disease validity (ClinGen):
ClinGen rates the evidence that HPD causes each of these diseases.
tyrosinemia type III (autosomal recessive): Definitive. Tyrosinemia type 3 is an inborn error of tyrosine metabolism characterised by mild hypertyrosinemia and increased urinary excretion of 4-hydroxyphenylpyruvate, 4-hydroxyphenyllactate and 4-hydroxyphenylacetate.
hawkinsinuria (autosomal dominant): Limited. Hawkinsinuria is an inborn error of tyrosine metabolism characterized by failure to thrive, persistent metabolic acidosis, fine and sparse hair, and excretion of the unusual cyclic amino acid metabolite, hawkinsin ((2-l-cystein-S-yl, 4-dihydroxycyclohex-5-en-1-yl)acetic acid), in the urine.
Homologues: Orthologues: chimpanzee HPD (99% identical), macaque HPD (97% identical), mouse Hpd (90% identical), guinea pig HPD (88% identical), pig HPD (87% identical), dog HPD (86% identical), rabbit HPD (83% identical), tropical clawed frog hpd (75% identical), rat Hpd (73% identical), zebrafish hpdb (71% identical), Caenorhabditis elegans hpd-1 (61% identical), Drosophila melanogaster Hpd (61% identical). Paralogues in human: HPDL (23% identical).
Diseases named in the same sentence as HPD in open-access papers:
HPD is named in the same sentence as 46 diseases in open-access papers, as found by Europe PMC text mining. Sharing a sentence is not in itself a finding about the gene and the disease. The quoted sentences say what the papers report.
lung carcinoma (7 papers, 2013 to 2025). "To determine the role of HPD in lung cancer, we first examined the expression of HPD in tissues from lung cancer patients." (PMID 31285420, 2019). "We established various HPD stable knockdown cell lines, and we found that depleting HPD downregulated cell proliferation of lung cancer cells." (PMID 31285420, 2019). "In this study, we found that HPD was highly expressed in lung cancer and its higher expression correlated with poor prognosis in lung cancer patients." (PMID 31285420, 2019). "We demonstrated that HPD is commonly upregulated in lung cancer and is important for cell proliferation and tumor growth through regulation of cell metabolism." (PMID 31285420, 2019). "A panel of lung cancer cell lines also showed higher expression of HPD compared with normal human bronchial epithelial cell line (BEAS-2B)." (PMID 31285420, 2019). "In summary, this study uncovers a new function of HPD in promoting PPP and tumor growth of lung cancer cells, and demonstrates that this previous unrecognized function of HPD is mediated through the G6PD–PPP flux axis." (PMID 31285420, 2019). "To address the functional consequence of HPD upregulation in lung cancer, we examined the effect of HPD on cell proliferation and tumor growth." (PMID 31285420, 2019). "Immunohistochemistry (IHC) staining showed that the expression of HPD was positive in 40 (83.3%) and strongly positive in 30 (62.5%) of the 48 lung cancer patients, which was significantly higher than in adjacent nontumor lung tissues." (PMID 31285420, 2019). "Previous studies have shown that HPD can be highly expressed in lung carcinoma." (PMID 34568735, 2021). "In conclusion, the Ad5/F35-APE1 siRNA recombinant adenovirus could efficiently inhibit the HpD-PDT-induced APE1 expression hence could significantly enhance the killing effect of HpD-PDT in lung cancer cells." (PMID 23509821, 2013). "HPD contributes to G6PD expression, thus enhancing the PPP flux and facilitating lung cancer growth." (PMID 39025830, 2024). "In our previous work, it was found that the tyrosine metabolizing enzyme HPD regulates the expression of G6PD, mediates the pentose phosphate pathway, and regulates glucose metabolic flux and DNA synthesis in lung cancer." (PMID 37786553, 2023). "For example, we previously found that 4-hydroxyphenylpyruvate dioxygenase (HPD), as a tyrosine-metabolizing enzyme, regulates the pentose phosphate pathway (PPP) flux to promote the growth of lung cancer." (PMID 35203444, 2022). "The main finding of this study is that HPD acts as an activator of the PPP, which is vital for growth of lung cancer cells." (PMID 31285420, 2019). "In this study, we demonstrated that the HPD–glucose-6-Phosphate Dehydrogenase (G6PD) axis enhanced the oxidative pentose phosphate pathway (PPP) flux and facilitated lung cancer growth." (PMID 31285420, 2019). "Moreover, exogenous expression of HPD significantly increased the G6PD enzyme activity, mRNA level and protein level in H1299, H226 lung cancer cells and 293T cells." (PMID 31285420, 2019). "Thus, this study reveals HPD as a novel regulator of LKB1–AMPK signaling-mediated HDAC10 nuclear location, which contributes to G6PD expression in promoting tumor growth, which is a promising target for lung cancer treatment." (PMID 31285420, 2019).
tyrosinemia (7 papers, 2018 to 2025). An autosomal recessive inherited metabolic disorder caused by mutations in the FAH, HPD, and TAT genes. "With regard to physiological states, in benign transient tyrosinemia, Tyr is temporarily elevated in newborns due to a combination of immaturity of the enzyme 4-hydroxyphenylpyruvate dioxygenase (4-HPPD) and a relative ascorbic acid deficiency." (PMID 39728402, 2024). "Decreased expression of 4-hydroxyphenylpyruvic acid dioxygenase (HPD), a key enzyme for tyrosine metabolism, is a cause of human tyrosinemia." (PMID 31537781, 2019). "Patients with mutations in the HPD gene are considered to have Type III Tyrosinemia and exhibit high level of tyrosine in blood, but otherwise appear to be largely asymptomatic." (PMID 30231914, 2018). "Decreased expression of 4-hydroxyphenylpyruvic acid dioxygenase (HPD) has been linked to tyrosinemia, yet the mechanism underlying the regulation of HPD expression is largely unknown." (PMID 31537781, 2019). "TYR3, also known as non-hepatorenal tyrosinemia, is caused by 4-hydroxyphenylpyruvate dioxygenase deficiency." (PMID 40265447, 2025). "Our findings demonstrate that decreased HPD expression resulting from non-genetic mutation or deficiency of HPD can be a potential cause of tyrosinemia and highlight that targeting regulation of HPD stability can be an additional approach for treating tyrosinemia with reduced expression of HPD." (PMID 31537781, 2019).
alkaptonuria (5 papers, 2021 to 2026). "Four patients, from three families, with alkaptonuria receiving 4-hydroxyphenylpyruvate dioxygenase-inhibiting nitisinone therapy, which lowers homogentisic acid and increases tyrosine, developed vitiligo." (PMID 34485014, 2021). "More recently, nitisinone — an inhibitor of 4-hydroxyphenylpyruvate dioxygenase (HPPD), approved for the treatment of hereditary tyrosinemia type I (HT-1) and alkaptonuria — has emerged as a potential systemic insecticide." (PMID 41525420, 2026). "Nitisinone (NTBC) is a specific inhibitor of 4-hydroxyphenylpyruvate dioxygenase (4-HPPD), utilized in treating metabolic disorders such as hereditary type I tyrosinemia and alkaptonuria by reducing the accumulation of toxic metabolites." (PMID 38765007, 2024).
Tyrosinemia type 1 (5 papers, 2017 to 2023). "Tyrosinemia type 1 is a monogenic IEM secondary to Fah1 gene mutations which can be partially stabilized by upregulation of enzyme 4-hydroxyphenylpyruvate dioxygenase (HPD) activity." (PMID 37545694, 2023). "Nitisinone is a competitive inhibitor of the enzyme 4-hydroxyphenylpyruvate dioxygenase approved for the treatment of hereditary tyrosinemia type 1." (PMID 33513899, 2021). "Hence, interaction of HPD and BHMT may result in a crosstalk between both pathways in order to control methionine levels, which may otherwise increase in parallel with fumaryl acetoacetate concentrations as observed in tyrosinemia type I." (PMID 29924862, 2018).
Tyrosinemia type 3 (5 papers, 2014 to 2022). "HPD encodes 4-hydroxyphenylpyruvate dioxygenase (HPPD), a key enzyme in tyrosine degradation whose Df causes autosomal recessive Tyrosinemia type 3, characterized by mental retardation." (PMID 28352227, 2017). "Decreased expression of HPD, a key metabolic enzyme in the phenylalanine and tyrosine catabolic pathway, contributes to tyrosinemia type III, which features elevated levels of blood tyrosine, tyrosine derivatives in urine, and neurological disorders." (PMID 31537781, 2019). "Tyrosinemia type III (OMIM 276710) is the rarest type of deficiency in the tyrosine metabolism pathway due to a lack of enzyme 4-hydroxyphenylpyruvate dioxygenase (HPPD)." (PMID 36471409, 2022).
hawkinsinuria (3 papers, 2017 to 2023). "Hawkinsinuria is caused by a mutation of the 4-hydroxyphenylpyruvate dioxygenase (4-HPPD, EC 1.13.11.27) gene, located in the chromosomal locus 12q24-qter, and is an autosomal dominant rare inborn error of metabolism characterized by acidosis and underdevelopment." (PMID 37384105, 2023).
hepatocellular carcinoma (3 papers, 2019 to 2025). A malignant tumor that arises from hepatocytes. "The downregulation of tyrosine metabolism pathway-related genes (HPD, HGD, GSTZ1, and FAH) was observed in hepatocellular carcinoma and indicated poor prognosis; however, investigation of dysregulation of tyrosine metabolism pathways in OSCC is lacking." (PMID 34422810, 2021).
bladder cancer (2 papers, 2021 to 2025). "In the same year, J. F. Kelly proved the elimination of bladder carcinoma in mice, by activating HpD with light." (PMID 34575408, 2021). "In 1976, another major event in the development of PDT occurred, when J. F. Kelly and M. E. Snell proceeded to the first human study of the effects of PDT in bladder cancer using HpD." (PMID 34575408, 2021).
glioma (2 papers, 2023 to 2024). A benign or malignant brain and spinal cord tumor that arises from glial cells (astrocytes, oligodendrocytes, ependymal cells). "Third, in glioma, increased protein levels of the tyrosine degradation pathway (HPD, HGD, and FAH) was correlated with higher PD-L1 expression, which promoted immune evasion by suppressing T-cell activity." (PMID 39592957, 2024). "To clarify the specific mechanism of tyrosine metabolizing enzymes regulating the malignant phenotype of glioma, we first calculated the optimal “cutpoint” using the R package algorithm and divided glioma patients into two groups according to the expression levels of HPD, HGD, and FAH." (PMID 37786553, 2023). "Taken together, these results suggest that the tyrosine metabolizing enzymes HPD, HGD, and FAH promote the malignant phenotype of glioma, which in turn exacerbates the poor prognosis of patients." (PMID 37786553, 2023). "On the other hand, tyrosine aminotransferase (TAT), HPD, HGD, and FAH were identified as unfavorable prognostic factors in glioma patients in the validation set." (PMID 37786553, 2023). "In the CGGA database, the expressions of HPD, HGD, and FAH were significantly elevated in high‐grade glioma and IDH wild‐type glioma." (PMID 37786553, 2023). "In all, the highly expressed HPD, HGD, and FAH in glioma modulate the TME, alter the abundance of immune cells, and promote immune evasion." (PMID 37786553, 2023). "In addition, abnormal expression of tyrosine metabolizing enzymes (HPD, HGD, and FAH) alters the TME of glioma." (PMID 37786553, 2023).
Hypertyrosinemia (2 papers, 2019). An increased concentration of tyrosine in the blood. "Although these reports indicate a critical role of HPD in hypertyrosinemia, the mechanism underlying the regulation of HPD expression is unclear." (PMID 31537781, 2019).
liver cancer (2 papers, 2022 to 2025). An epithelial or non-epithelial malignant neoplasm that arises from the liver. "Previous studies also showed that genes from tyrosine metabolism reprogramming (TAT, HPD, HGD, GSTZ1, and FAH) may be used as prognostic biomarkers in liver cancer." (PMID 35847355, 2022).
ovarian carcinoma (2 papers, 2022 to 2025). A malignant neoplasm originating from the surface ovarian epithelium. "Disrupting HPD's RNA‐binding function effectively suppresses tumor growth and enhances therapeutic sensitivity, highlighting its potential as a novel target for ovarian cancer treatment." (PMID 40491422, 2025). "Unexpectedly, it is discovered that HPD functions as an RNA‐binding protein (RBP) to drive ovarian cancer progression." (PMID 40491422, 2025). "We collected 20 normal ovarian tissues and 20 ovarian cancer tissues, and detected the protein levels of HPD, TPI, and ENO1 by WB." (PMID 40491422, 2025). "In the current study, we surprisingly demonstrate that HPD works as an RBP to promote ovarian cancer glycolysis flux by increasing global mRNA translation, including glycolytic metabolic enzymes TPI and ENO1, thereby promoting the tumorigenesis of ovarian cancer." (PMID 40491422, 2025). "In this study, we explored whether targeting HPD's RBP‐dependent function could increase the sensitivity of ovarian cancer to Taxol treatment." (PMID 40491422, 2025). "Furthermore, as the protein level of HPD increases in ovarian cancer cell lines, so does the protein level of TPI and ENO1." (PMID 40491422, 2025). "We identified the moonlighting function of HPD, which exerts as a non‐canonical RBP to promote translation in ovarian cancer." (PMID 40491422, 2025). "We noted that the mRNA of UBA2, GLO1, TUFT1, HPD, and GBF1 were upregulated in the ovarian cancer samples in comparison to the control samples." (PMID 35992817, 2022). "Collectively, our results demonstrate that the metabolic enzyme HPD acts as a non‐canonical RBP to promote global mRNA translation efficiency in ovarian cancer, adding another dimension to the regulation of ovarian cancer development of HPD with moonlighting function." (PMID 40491422, 2025). "Given that HPD controls translation regulation of TPI and ENO1, we next wanted to find out whether TPI and ENO1 are co‐expressed with HPD in human ovarian cancer." (PMID 40491422, 2025).
prostate carcinoma (2 papers, 2021 to 2022). A carcinoma that arises from epithelial cells of the prostate gland. "CRABP2, HPD, ZEB2 and CDK5R1 are the common DEGs both in breast and prostate cancer." (PMID 33407865, 2021).
brain glioma (1 paper, 2025). A malignant glioma that involves the brain. "A study assessed the efficacy of PDT utilizing HpD as an adjunctive treatment for brain gliomas." (PMID 40177536, 2025).
colorectal cancer (1 paper, 2025). A primary or metastatic malignant neoplasm that affects the colon or rectum. "In particular, it is demonstrated that HPD regulates colorectal cancer ferroptosis by methylating SLC7A11/GPX4 through a moonlighting function." (PMID 41317403, 2025).
Failure to thrive (1 paper, 2024). Failure to thrive (FTT) refers to a child whose physical growth is substantially below the norm. "Fah–/– mice, a model of HT1, universally develop hepatitis, failure to thrive, and death in the absence of nitisinone (NTBC), a repurposed herbicide that blocks the activity of 4-hydroxyphenylpyruvate dioxygenase (HPD) in the tyrosine catabolic pathway." (PMID 38950310, 2024).
glioblastoma (1 paper, 2019). The most malignant astrocytic tumor (WHO grade IV). "There was a strong association between HpD uptake and survival among treated patients (Hazard Ratio = 0.26, p = 0.001) and the median overall survival for glioblastoma patients after PDT was 24.0 months." (PMID 32039232, 2019). "HpD concentration in tumor tissue compared to survival after PDT was evaluated in 58 glioblastoma patients." (PMID 32039232, 2019). "A similar study evaluating HpD mediated PDT for high grade gliomas including 78 glioblastoma patients was performed." (PMID 32039232, 2019). "The effects of HpD or porfimer sodium mediated PDT on glioblastomas was evaluated in 17 patients." (PMID 32039232, 2019). "An early study evaluating the efficacy of HpD mediated PDT enrolled 18 glioblastoma patients." (PMID 32039232, 2019).
Lewis lung carcinoma (1 paper, 2017). "Early studies comparing the photodynamic efficacy of Pba with Hematoporphyrin derivative (HpD) in Lewis lung carcinoma in mice found that Pba is a stronger PS as compared to HpD due to its longer wavelength of absorbance in the red region of the spectrum." (PMID 28430624, 2017).